GPX7 (glutathione peroxidase 7)
Diseases named in the same sentence as GPX7 in open-access papers (continued):
Sharing a sentence is not in itself a finding about the gene and the disease.
glioma (continued). "Thus, the role of GPX7 in glioma, whether it could promote the pathological process of glioma or serves as a clinical therapeutic target, remained elusive." (PMID 33750478, 2021). "However, the mechanisms by which GPX7 might exert its actions in the development of glioma remain to be elucidated." (PMID 35127512, 2021). "Consequently, we found that GPX7 was highly expressed in glioma." (PMID 33750478, 2021). "Furthermore, miR-29b suppressed GPX7 expression post-transcriptionally in glioma." (PMID 35127512, 2021). "Furthermore, our study brings key insights into the significant effect of GPX7 in modulating both immune molecules and in immune cell infiltration in the microenvironment of gliomas, which might impact the patient outcome, opening up future opportunities to regulate the local immune response." (PMID 35440701, 2022). "Therefore, upregulation of GPX7 observed in gliomas might reflect the oxidative stress that these tumors experience during their development, as supported by its positive correlation with the cell cycle, chemotherapy treatment, and inflammatory pathways and cells." (PMID 35440701, 2022). "Despite reaching a preliminary conclusion on how GPX7 regulates glioma by GSEA analysis, the biological behavior of glioma cannot be fully regulated by a single factor due to the complex pathological process of glioma." (PMID 33750478, 2021). "Therefore, targeting GPX7 may help reverse the erastin resistance in glioma treatment." (PMID 35127512, 2021). "However, the biological functions of GPX7 in glioma are still unknown." (PMID 35127512, 2021). "However, it was also reported that the KD reduced ROS levels in gliomas, accompanied by slowed tumor growth and changes in ROS modulating genes, including cyclooxygenase-2 (COX-2), glutathione peroxidase 7 (Gpx7) and peroxiredoxin 4 (Prdx4)." (PMID 36432618, 2022). "By assembling the Cancer Cell Line Encyclopedia (CCLE), we further explored whether the overexpression pattern of GPX7 detected in LGG and GBM tissues would be similar in glioma cell lines." (PMID 35440701, 2022). "In glioma, our work found that GPX7 knockdown alone exerted no direct effect on tumor growth, although ferroptosis-related oxidative stress was promoted." (PMID 35127512, 2021). "Additionally, according to the GEPIA database, the expression of GPX7 was significantly higher in glioblastoma (GBM) and low-grade gliomas (LGG) than normal tissues." (PMID 33750478, 2021). "So far, there is no relevant report of the function of GPX7 in glioma." (PMID 33750478, 2021). "To explore whether all miR-29 family members modulate GPX7 expression in glioma, we mined tumor gene expression profiles in TCGA and CGGA databases and found that only miR-29b-3p expression level was inversely correlated with GPX7 expression in the two databases." (PMID 35127512, 2021). "In addition, GPX7 knockdown and erastin cotreatment significantly inhibited the migratory and invasive abilities and increased apoptosis of glioma cells, while GPX7 knockdown alone did not exhibit obvious effects." (PMID 35127512, 2021). "CCK-8 assay revealed that GPX7 knockdown alone did not affect the proliferation of glioma cells." (PMID 35127512, 2021).
breast carcinoma (7 papers, 2010 to 2023). "As studies of the functions of GPx5, GPx6 and GPx7 in the development of breast cancer are limited, it is difficult to determine their underlying mechanisms." (PMID 32571353, 2020). "More recently, GPx7 (NPGPx) has been described; like GPx5 it is a cysteine-based isoform, and is thought to prevent oxidative stress in breast cancer cell lines and protein folding in the endoplasmic reticulum." (PMID 25268836, 2014). "In contrast to the closely related GPX7, which has been posited as a tumor suppressor, emerging evidence has implicated GPX8 as a pro-tumorigenic factor in various cancers such as gastric, lung, and breast cancer." (PMID 36750850, 2023). "GPX7 protein expression in breast cancer was significantly increased." (PMID 32782436, 2020). "However, the other four GPXs family genes (GPX1, GPX5, GPX6 and GPX7) showed no statistical diagnostic values in breast cancer." (PMID 32782436, 2020). "GPX4, GPX6 and GPX7 had no significant predictive values for prognosis of breast cancer." (PMID 32782436, 2020).
Obesity (7 papers, 2013 to 2025). Accumulation of substantial excess body fat. "Several SNP variations associated with obesity and insulin resistance have been described so far, especially GPx1 and GPx7 genes." (PMID 40428311, 2025). "It was also shown that decreased GPx7 expression was found in several populations having SNP variations near this gene, and this condition was associated with obesity." (PMID 40428311, 2025). "Too much data regarding the association between obesity and GPx1, GPx3, GPx4, and GPx7 has been reported." (PMID 29132311, 2017). "Of note, Gpx7 deficiency is believed to increase intracellular OS and especially ROS levels, which elevates adipogenesis together with white adipose‐tissue mass, thereby leading to obesity in both mice and humans." (PMID 34626080, 2021). "Finally, it can be concluded that these GPx SNP variants with enzymatic activity are involved in the protection against metabolic complications caused by obesity, while the sensor transducer GPx7 regulates the body’s response to elevated ROS synthesis in obesity." (PMID 40428311, 2025). "Previous studies have reported associations of SNPs SOD2 rs4880, GPX7 rs835337, GPX1 rs1050450, CAT rs1001179 with obesity, body mass index and body fat in Brazilian, Mexican, British, Finnish, Chinese, Caucasian, and African–American adult populations." (PMID 40867795, 2025). "A total of 1675 children with normal weight and 1271 children with obesity were included to assess the association of four SNPs, SOD2 rs4880, GPX7 rs835337, GPX1 rs1050450, and CAT rs1001179, with obesity." (PMID 40867795, 2025). "In previous studies, the SNPs SOD2 rs4880, GPX7 rs835337, GPX1 rs1050450, and CAT rs1001179 have been associated with lipid peroxidation, obesity, and their metabolic complications in adult populations." (PMID 40867795, 2025). "In summary, GPXs with enzymatic activity seem to be involved in the protection against obesity-derived metabolic complications, whereas the sensor/transducer GPX7 regulates responses against ROS in the earlier steps of obesity development." (PMID 24562334, 2014). "Regarding genetic variations, SNPs associated with obesity and insulin resistance have been described for the GPX1 and GPX7 genes." (PMID 24562334, 2014). "In the present study, we investigated the direct and modulatory effects of four antioxidant enzyme SNPs (SOD2 rs4880, GPX1 rs1050450, GPX7 rs835337, and CAT rs1001179) on the relationships among obesity-related oxidative stress markers in Mexican children." (PMID 40867795, 2025). "We aimed to assess the direct and modulatory effects of SNPs in antioxidant genes (SOD2 rs4880, GPX1 rs1050450, GPX7 rs835337, CAT rs1001179) on the relationships among obesity-related oxidative stress markers in Mexican children." (PMID 40867795, 2025). "Therefore, the present study aims to investigate both the direct and modulatory effects of four SNPs in antioxidant genes (SOD2 rs4880, GPX1 rs1050450, GPX7 rs835337, CAT rs1001179) on the relationships among obesity-related oxidative stress markers in Mexican children." (PMID 40867795, 2025).
gastric cancer (5 papers, 2017 to 2024). A primary or metastatic malignant neoplasm involving the stomach. "We found that the suppression of growth rates by GPX7 is associated with a significant reduction in the proliferative capacity of gastric cancer cells, as indicated as lower EdU rate and Ki-67 positive rate." (PMID 28903346, 2017). "Because GPX7 promoter has a large CpG island, we investigated the GPX7 promoter hypermethylation as a cause of GPX7 downregulation in gastric cancers." (PMID 28903346, 2017). "They detected downregulation of GPX7 in all seven gastric cancer cell lines as well as in approximately half of the human gastric cancer samples." (PMID 39409942, 2024). "According to in vitro studies, reconstituted GPX7 inhibited the development of stomach cancer cells in two-dimensional and three-dimensional organotypic cell culture models." (PMID 35069731, 2022). "In contrast to all seven gastric cancer cell lines and 56% (25/45) of gastric cancer samples, only 13% (6/45) of normal samples showed DNA hypermethylation (>10% methylation level) of the GPX7 promoter (P < 0.0001)." (PMID 35069731, 2022). "GPX7, on the other hand, was shown to be downregulated in all seven cancer cell lines examined and in almost half of all human gastric cancer cases (22/45)." (PMID 35069731, 2022). "We, therefore, tested the effect of GPX7 reconstitution on gastric cancer cells (AGS and MKN45) using colony formation and 3D organotypic culture assays." (PMID 28903346, 2017). "Using pyrosequencing, we quantitated GPX7 promoter methylation level in these gastric cancers and their matched normal samples." (PMID 28903346, 2017). "We found that GPX7 promoter region is highly hypermethylated in all gastric cancer cell lines that we tested, showing high DNA methylation levels of all tested CpG nucleotides (range 50%–100%)." (PMID 28903346, 2017). "In conclusion, our results suggest that GPX7 gene inactivation by promoter methylation is a frequent event in gastric cancer." (PMID 28903346, 2017). "In the present study, we examined GPX7 gene expression, promoter methylation status, and its potential function in suppressing growth of gastric cancer cells." (PMID 28903346, 2017). "Here, we show that another GPX family member, GPX7 is also frequently silenced/downregulated in gastric cancers." (PMID 28903346, 2017). "In this study, we investigated the expression, regulation, and molecular function of GPX7 in gastric cancer using 2D and 3D in vitro models and de-identified human tissue samples." (PMID 28903346, 2017). "In vitro assays showed that reconstitution of GPX7 significantly suppressed gastric cancer cell growth in both 2D and 3D organotypic cell culture models." (PMID 28903346, 2017). "We found that 22 out of 45 (48.8%) primary gastric cancers showed a significant downregulation of GPX7 as compared to their normal adjacent samples." (PMID 28903346, 2017). "Reconstitution of GPX7 in gastric cancer cells significantly suppressed tumor cell growth through inhibition of proliferative capacity and induction of cell death." (PMID 28903346, 2017). "We detected downregulation of GPX7 in all 7 gastric cancer cell lines that we tested and in approximately half (22/45) of human gastric cancer samples, as compared to histologically normal gastric tissues." (PMID 28903346, 2017). "To explore the potential mechanism for the suppression of gastric cancer cell growth, we first checked if GPX7 has an effect on cell proliferation of gastric cancer cells." (PMID 28903346, 2017). "In the current study, we found that silence of GPX7 expression occurred in all gastric cancer cell lines examined and downregulation of GPX7 was found in about half of primary gastric cancer tissues." (PMID 28903346, 2017). "Next, we checked GPX7 mRNA expression in 45 paired gastric cancer tissue samples and corresponding histologically normal adjacent tissue samples." (PMID 28903346, 2017).
gastric cancer (continued). "To examine GPX7 gene expression in gastric cancers, we first carried out a quantitative real-time reverse transcription PCR (qRT-PCR) analysis of mRNA expression in 7 gastric cancer cell lines." (PMID 28903346, 2017). "GPX7 gene expression was silenced in all 7 gastric cancer cell lines examined, suggesting that GPX7 may disfavor tumor cell survival and/or growth." (PMID 28903346, 2017). "Quantitative bisulfite pyrosequencing methylation analysis demonstrated DNA hypermethylation (> 10% methylation level) of GPX7 promoter in all 7 gastric cancer cell lines and in 56% (25/45) of gastric cancer samples, as compared to only 13% (6/45) in normal samples (p < 0.0001)." (PMID 28903346, 2017). "Tumorigenesis and gastric cancer progression may be influenced by GPX7 gene inactivation." (PMID 39409942, 2024). "Based on our data, the DNA hypermethylation of GPX7 promoter is likely the major mechanism for the dysfunction of GPX7 in gastric cancer, although other mechanisms such as miRNA regulation may also be involved in a subset of tumors and needs to be further studied." (PMID 28903346, 2017). "Based on our results and earlier reports, we suggest that downregulation of GPX7 and GPX3 denotes a severe dysfunctional antioxidant system in gastric cancer cells." (PMID 28903346, 2017).
diabetes (4 papers, 2014 to 2025). "Eleven genes in the Glutathione metabolism pathway (Gpx7, Gss, Gsta3, Gstm2, Gstm5, Gstm7, Gsto1, Gstp1, Gstt1, Gstt2 and Mgst2) were observed in type 2 diabetes mellitus." (PMID 25788156, 2015). "To examine whether altered expression of some of the identified candidate genes in the islet mQTL/eQTL analyses affect β-cell function and thereby potentially the development of diabetes, we silenced the expression of three selected genes; Gpx7, Gstt1 and Snx19, in clonal β-cells." (PMID 25375650, 2014). "This revealed an enrichment for proteins involved in response to oxidative stress and cellular oxidant detoxification, such as glutathione peroxidase 7 (GPX7) and selenoprotein P (SEPP1), in line with oxidative stress being a feature of diabetes." (PMID 40829182, 2025).
sarcoma (3 papers, 2022 to 2023). A usually aggressive malignant neoplasm of the soft tissue or bone. "Notably, amplification was the most common type of mutation, and S100A9, IPCEF1, and GPX7 were frequently amplified in sarcoma." (PMID 35143416, 2022). "The authors describe that GPx-7 was overexpressed in brain, breast, esophageal, gastric, and liver cancers as well as leukemia, melanoma, myeloma, and sarcoma and underexpressed in lymphomas." (PMID 37761814, 2023).
thyroid cancer (3 papers, 2015 to 2022). "As a conclusion, according to our data PC Cl3, PC PTC1, PC E1A cell model systems corresponded to human NOX2, NOX4, SOD3, CATALASE, GPX5, and GPX7 gene expressions in thyroid cancer." (PMID 26664298, 2015). "Glutathione peroxidase family showed variable gene expression: GPX1 and GPX2 expression analysis suggested minor increase in mRNA synthesis, GPX3, GPX5, and GPX7 expression was downregulated in thyroid cancers, whereas GPX4 expression did not change." (PMID 26664298, 2015).
astrocytoma (2 papers, 2022 to 2023). "Notably, in both cohorts, GPX7 was prominently higher in GBM than in LGG tumors (Oligoastrocytoma; Oligodendroglioma; Astrocytoma), while the expression of GPX7 was significantly higher as pathological grade increased." (PMID 35440701, 2022).
colon adenocarcinoma (2 papers, 2021 to 2022). "A cluster of 13 CpG loci (11 genes) were identified that displayed differential methylation in colon adenocarcinoma (COAD) (N = 289) compared to normal colon tissues (N = 38): ZNF671, TWIST1 (two CpG loci), TMEFF2, TM6SF1, GAS7, MAL, HIN1 (two CpG loci; SCGB3A1), COL6A2, AKR1B1, GPX7, ARHGEF7)." (PMID 34903270, 2021).
hepatocellular carcinoma (2 papers, 2021 to 2024). A malignant tumor that arises from hepatocytes. "GPX4 and GPX7 were overexpressed in the tissues of human hepatocellular carcinoma." (PMID 34531924, 2021). "GPX7, along with GPX4, is known to be overexpressed in hepatocellular carcinoma tissues." (PMID 39684755, 2024).
ischaemic stroke (2 papers, 2022 to 2025). "Although this study reveals the potential role of GPX7 and its associated oxidative stress pathway in ischemic stroke, certain limitations remain." (PMID 40563300, 2025). "In this study, we preliminarily revealed a potential association between GPX7 and oxidative stress status in ischemic stroke (IS) model by integrating multi-omics analysis and experimental validation." (PMID 40563300, 2025). "In conclusion, the present study systematically revealed for the first time the closely related regulator of oxidative stress in ischemic stroke (IS), GPX7, at a multi-omics level." (PMID 40563300, 2025). "The aim of this study was to elucidate the role of the oxidative stress-related gene GPX7 as a potential therapeutic target in ischemic stroke and to assess the therapeutic potential of glutathione as a novel intervention strategy." (PMID 40563300, 2025). "Future studies should further resolve the precise molecular interactions between GPX7 and Nrf2, which may provide new insights into therapeutic strategies for ischaemic stroke based on redox regulation." (PMID 40563300, 2025).
non-alcoholic steatohepatitis (2 papers, 2023 to 2025). "It is established that GPX7 can ameliorate nonalcoholic steatohepatitis by regulating oxidative stress levels." (PMID 40362390, 2025). "In studies of non-alcoholic steatohepatitis due to oxidative stress, overexpression of GPX7 in LX-2 cells will result in inhibition of ROS production and a decrease in the expression of profibrotic and pro-inflammatory genes." (PMID 36937839, 2023). "GPX7 may improve non-alcoholic steatohepatitis by regulating oxidative stress levels." (PMID 36937839, 2023).
brain cancer (1 paper, 2022). A primary or metastatic malignant neoplasm affecting the brain. "Subsequently, we focused our analysis on the differential expression of GPX7 in all brain cancer datasets deposited on Oncomine." (PMID 35440701, 2022).
brain tumors (1 paper, 2023). "However, the role of GPx-7 in the development of brain tumors is not well known." (PMID 37761814, 2023).
esophageal cancer (1 paper, 2021). A primary or metastatic malignant neoplasm involving the esophagus. "Epigenetic inactivation of GPX7 may be an important mechanism of esophageal cancer." (PMID 33708772, 2021).
Intellectual disability (1 paper, 2024). "The A54T mutation in GPx7 identified through genomic screening was associated with patients exhibiting intellectual disability, with a significant destabilizing effect (3.38 kcal/mol) on the protein." (PMID 39796732, 2024). "Background/Objectives: Somatic and genetic mutations in glutathione peroxidases (GPxs), including GPx7 and GPx8, have been linked to intellectual disability, microcephaly, and various tumors." (PMID 39796732, 2024).
liver fibrosis (1 paper, 2024). "The fact that GPX7 is overexpressed in response to HSC activation and that it controls the production of pro-fibrotic genes by controlling intracellular ROS levels suggests that oxidative stress participates in the development of liver fibrosis through a progression of NASH." (PMID 39290493, 2024).
low grade glioma (1 paper, 2022). A grade I or grade II glioma arising from the central nervous system. "Our results consistently demonstrated that upregulation of GPX7 is tightly modulated by epigenetic processes, which also impacted the overall survival of patients with low-grade gliomas (LGG)." (PMID 35440701, 2022).
lung carcinoma (1 paper, 2023). "In addition, a study of 400 lung cancer patients found that the glutathione peroxidase 7 (GPX-7) gene and ABCC4 SNPs were associated with peripheral neuropathy following chemotherapy, attributing to the effect of SNP on gene expression." (PMID 37563730, 2023).
motor neuron degeneration (1 paper, 2022). "Deletion of the nonselenocysteine-containing phospholipid hydroperoxide glutathione peroxidase (NPGPx or GPx7) in mice phenocopies the locomotor deficits and motor neuron degeneration characteristic of ALS." (PMID 36359905, 2022).
myocardial ischemia (1 paper, 2023). A disorder of cardiac function caused by insufficient blood flow to the muscle tissue of the heart. "Eight genes (Aif1, Apoe, Arg1, Col1a1, Gpx7, Hmox1, Mmp14, and Sirpa) were significantly differentially expressed in the rat myocardial ischemia-reperfusion model." (PMID 36826575, 2023).